MCL1 (MCL1 apoptosis regulator, BCL2 family member)
Diseases named in the same sentence as MCL1 in open-access papers (continued):
Sharing a sentence is not in itself a finding about the gene and the disease.
neuroblastoma (continued). "The MCL-1 inhibitor S63845 induced some loss of viability in NB6 cells at 10 μM, confirming that MCL-1 may also be a relevant therapeutic target in neuroblastoma." (PMID 32203216, 2020). "In-vitro inhibition of Mcl-1 sensitized neuroblastoma cell lines to ABT-199." (PMID 30885150, 2019). "Therefore, there is ongoing research to identify an inhibitor of Bcl-2 and Mcl-1 in N-Myc amplified neuroblastomas." (PMID 30885150, 2019). "Therefore, combined Bcl-2/Mcl-1 inhibition should be further elucidated as a treatment option in neuroblastoma with N-Myc amplification." (PMID 30885150, 2019). "Therefore, we evaluated the effect of TW-37, which inhibits Mcl-1 and Bcl-2 with almost the same affinity and which has also low affinity to Bcl-xL in neuroblastoma cell lines." (PMID 30885150, 2019). "Therefore, BH antagonism has become a treatment approach in neuroblastoma, and several agents have been developed with different selectivity to inhibit Bcl-2 and Mcl-1." (PMID 30885150, 2019). "In summary, miR-193b overexpression induces a cell cycle arrest and apoptosis in neuroblastoma by reducing the expression of MYCN, cyclin D1 and MCL-1, three important oncogenes in neuroblastoma whose inhibition by inhibitors have shown promising results in preclinical testing." (PMID 29719597, 2018). "Interestingly, it has been reported that treatment of neuroblastoma cells with venetoclax can lead to increased levels of MCL1, resulting from a decreased expression of NOXA and increased stabilization by BIM." (PMID 28915653, 2017). "Moreover, knockdown of MCL1 combined with venetoclax treatment results in synergistic growth inhibition of neuroblastoma cells." (PMID 28915653, 2017). "Therefore, we determined BCL2 and MCL1 RNA and protein expression levels by RT-qPCR and Western Blotting, respectively, in a panel of neuroblastoma cell lines." (PMID 28915653, 2017). "In order to assess whether combined treatment of ABT-263 and idasanutlin could have a broad therapeutic applicability in neuroblastoma, we evaluated both compounds in 10 human neuroblastoma cell lines with varying MCL1 and BCL2 expression levels." (PMID 28915653, 2017). "Therefore, in MYCN-amplified neuroblastoma, MLN8237 inhibits p4E-BP1, leading to loss of eIF4G:eIF4E complex-mediated MCL-1 protein translation." (PMID 26859456, 2016). "Although in contrast to our study, depletion of granulocytic MDSC did not alter tumor incidence in neuroblastoma, they underline the importance of Mcl-1 in the survival of granulocytic MDSC." (PMID 25871384, 2015). "Interestingly, high expression levels of Bcl-2 or Mcl-1 correlated with advanced disease in neuroblastoma." (PMID 23420072, 2013). "Despite the established relevance of MCL1 in neuroblastoma biology and therapy response, and 1q gain as a marker of poor prognosis this gain was not previously linked to MCL1 activity in neuroblastoma." (PMID 40694850, 2025). "While a prominent role of MCL1 in chemoresistant cancer has been described in multiple studies, the loss of sensitivity to BCL2/BCL-XL inhibitors observed here may be more controversial and potentially limited to neuroblastoma." (PMID 37723317, 2023). "Therefore, targeting these spliceosomal components could be of interest in re-sensitizing MCL1-dependent neuroblastoma cells to Bcl-2 inhibitors." (PMID 34065983, 2021). "Therefore, combined inhibition of Bcl-2/Mcl-1 e.g. by TW-37 in N-Myc amplified neuroblastoma may represent an interesting therapeutic strategy." (PMID 30885150, 2019). "Therefore, combined inhibition of Bcl-2/Mcl-1 by TW-37 in N-Myc amplified neuroblastoma may represent an interesting therapeutic strategy." (PMID 30885150, 2019). "Further analysis demonstrated that the Mcl-1 inhibitor NOXA, encoded by PMAIP1, was significantly higher in N-Myc amplified neuroblastomas suggesting that increased NOXA expression was a contributing factor to ABT-199 sensitivity observed in N-Myc amplified neuroblastoma cells." (PMID 30885150, 2019).
neuroblastoma (continued). "Treatment with S63845 (MCL-1 inhibitor) or A1331852 (BCL-XL inhibitor) reduced viability and induced apoptosis in a subset of neuroblastoma cell lines, due to the release of pro-apoptotic proteins from BCL-XL- or MCL-1-mediated sequestration." (PMID 35568716, 2022). "Nevertheless, PUMA-derived helices in the form of SAHBs, which have the capacity to bind BAX or Bcl-xL/Mcl1 as dual anti-apoptosis inhibitors that induce BAX activation, have shown some encouraging outputs in overcoming chemoresistance in neuroblastoma cells." (PMID 34753495, 2021). "The silencing of MCL-1 was shown to sensitize or prime cancer cells to cytotoxic chemotherapy and BCL-2 family antagonists in ALL, rhabdomyosarcoma, and neuroblastoma." (PMID 31652776, 2019). "Increased expression of MCL1 is a known resistance factor against treatment with BCL2 antagonists in various cancer types, including neuroblastoma." (PMID 28915653, 2017). "Transgenic expression of MCL1, however, indirectly slows down BECN1 activation by sequestering NOXA away from BCLXL, as NOXA binds MCL1 with higher affinity than BCLXL in neuroblastoma cells." (PMID 28415610, 2017). "BIM displacement from BCL-2 to MCL-1 also occurred in vivo, confirming the pivotal role of MCL-1 in the biological mechanism by which neuroblastoma cells can escape from ABT199-induced apoptosis." (PMID 27056887, 2016). "Evaluation of the BCL-2, MCL-1, BCL-XL, BCL-W and BIM protein levels showed significantly higher BCL-2 levels in the sensitive neuroblastoma cell lines CHP126, KCNR and SJNB12 compared with the insensitive cell lines." (PMID 27056887, 2016). "MCL-1 knockdown in CHP126, KCNR and SJNB12 using two different shRNAs sensitized the neuroblastoma cell lines to ABT199 treatment." (PMID 27056887, 2016). "We observed that ABT199 treatment of the high BCL-2-expressing neuroblastoma cell lines CHP126, KCNR and SJNB12 indeed resulted in strongly increased MCL-1 levels, while the other anti-apoptotic proteins and the pro-apoptotic protein BIM were not affected." (PMID 27056887, 2016). "In vitro inhibition of MCL-1 sensitized neuroblastoma cell lines to ABT199, confirming the pivotal role of MCL-1 in ABT199 resistance." (PMID 27056887, 2016). "Effects of MCL-1 inhibition on the sensitivity of neuroblastoma cell lines CHP126, KCNR and SJNB12 to ABT199 were additionally studied using the selective MCL-1 inhibitor A-1210477." (PMID 27056887, 2016). "We used the neuroblastoma SH-SY5Y cell model, that expressed consistent levels of Mcl-1 and underwent similar modulations as U937 and Jurkat cells following treatment with UNBS1450." (PMID 26068790, 2015). "In vitro profiling of neuroblastoma cells using BH3-domain peptides revealed that, in addition to Mcl-1, also other antiapoptotic Bcl-2 proteins can confer resistance to chemotherapy." (PMID 23420072, 2013). "In neuroblastoma cells, alcohol exposure reduced protein levels of serine/arginine-rich splicing factor 1 (SRSF1) and shifted the alternative splicing of the MCL1 antiapoptotic protein towards the shorter isoform (Mcl-1S) over the long isoform (Mcl-1L)." (PMID 38396082, 2024). "Since we and others have recently shown that BH3-mimetics and in particular inhibitors of MCL1 or BCL-XL may increase the cytotoxicity of NK cells, we asked whether NK cells may be able to combat chemoresistance in neuroblastoma." (PMID 37723317, 2023). "Furthermore, MCL-1 knockdown induced apoptosis and increased sensitivity to both etoposide and doxorubicin in cell line models of neuroblastoma, in a mechanism also understood to involve the release of BIM from MCL-1 sequestration." (PMID 35568716, 2022). "All tested BH3-mimetics were able to induce apoptosis in neuroblastoma cell lines, indicating that not only BCL-2 but also BCL-XL and MCL-1 may be promising therapeutic targets." (PMID 32203216, 2020).
neuroblastoma (continued). "ABT-737, that binds with subnanomolar affinity to Bcl-2, Bcl-W and Bcl-xL, but has no appreciable affinity for Mcl-1, has shown to induce cell death in neuroblastomas." (PMID 30885150, 2019). "Additionally, neuroblastoma cells can acquire resistance to the BCL-2 inhibitor ABT-737 by upregulating EGFR and develop a dependence on MCL-1, which can be effectively countered by combining erlotinib with a BCL-2 inhibitor." (PMID 31150457, 2019). "Consistently, in another study, ABT-737 showed single-agent activity against only BIM:BCL-2 and not BIM:MCL-1-primed neuroblastoma-derived xenografts." (PMID 31652776, 2019). "This assumption is confirmed by a recent study, which demonstrated that neuroblastoma cells might survive ABT-199 treatment, a specific Bcl-2 inhibitor, due to acute upregulation of Mcl-1." (PMID 30885150, 2019). "Functionally, miR-193b induces a G1 cell cycle arrest and cell death in neuroblastoma cell lines by reducing the expression of MYCN, Cyclin D1 and MCL-1, three important oncogenes in neuroblastoma of which inhibition has shown promising results in preclinical testing." (PMID 29719597, 2018). "We however observed increased protein levels of the apoptotic mediators PUMA and BAX upon idasanutlin treatment of neuroblastoma cells, but no downregulation of MCL1 protein or any effects on BCL2 protein abundance." (PMID 28915653, 2017). "We observed that neuroblastoma cells express either BCL2, MCL1 or both." (PMID 28915653, 2017). "Our findings suggest that neuroblastoma patients with high BCL-2 and BIM/BCL-2 complex levels might benefit from combination treatment with ABT199 and compounds that inhibit MCL-1 expression." (PMID 27056887, 2016). "To more directly address whether inhibition of protein translation contributes to MCL-1 downregulation following MLN8237 treatment, we first measured the effects of MLN8237 on global protein translation in MYCN-amplified neuroblastoma cells." (PMID 26859456, 2016). "Taken together, the results presented in this study strongly suggest that children with neuroblastoma tumors expressing high levels of BCL-2 and the BIM/BCL-2 complex might benefit from combined treatment with ABT199 and compounds that inhibit MCL-1." (PMID 27056887, 2016). "Strategies that prevent Mcl-1 decrease, by including overexpression of a non-ubiquitinable form of Mcl-1 and inhibition of the proteasome, protected the neuroblastoma SH-SY5Y cells from UNBS1450-induced apoptosis." (PMID 26068790, 2015). "PI3K/Akt signaling is involved in Mcl-1 induction, targeting this pathway by newly developed PI3K inhibitor PI103 is showed to suppress Mcl-1 and induced apoptosis and restore sensitivity to TRAIL-induced apoptosis in neuroblastoma." (PMID 24529193, 2014). "Mcl-1 was upregulated after bortezomib exposure in all neuroblastoma cell lines whereas no change was identified in Bcl2, XIAP, survivin and Bcl-xl expression after bortezomib treatment." (PMID 18534018, 2008). "Moreover, neuroblastoma cell lines with 1q21 gain are significantly more dependent on MCL1 compared to cell lines without in the DepMap CRISPR screening dataset." (PMID 40694850, 2025). "This suggests that increased MCL1 activity through low-amplitude copy number gain in neuroblastoma may contribute to an aggressive phenotype in tumors without MYCN amplification, which is the strongest predictor of poor prognosis in neuroblastoma tumors." (PMID 40694850, 2025). "However, N-Myc amplified neuroblastomas could be further sensitized to ABT-199 with the Aurora Kinase A inhibitor MLN8237, which results in a downregulation of Mcl-1." (PMID 30885150, 2019). "We showed that neuroblastoma cells might survive ABT199 treatment due to its acute upregulation of the anti-apoptotic BCL-2 family protein myeloid cell leukaemia sequence 1 (MCL-1) and BIM sequestration by MCL-1." (PMID 27056887, 2016).
neuroblastoma (continued). "The effect of selective BH3-mimetics targeting MCL1 may further be increased by combination with cellular immunotherapy, thus opening up the possibilities of a safe and non-toxic combination for the treatment of relapsed neuroblastoma." (PMID 37723317, 2023). "We found that ATF5 knockdown reduced the expression of BCL-2 and MCL-1, but not of BMF, in adherent neuroblastoma cells." (PMID 38014922, 2023). "In some neuroblastoma mouse models, it was shown that ABT-199 treatment induced growth inhibition rather than apoptosis, due to MCL-1 upregulation and subsequent BIM sequestration by MCL-1." (PMID 35568716, 2022). "The molecular mechanisms of cell death induced by ABT-199 in neuroblastoma have already been elucidated in previous studies;29,30 however, so far the mechanisms of cell death induced by selective inhibitors of BCL-XL or MCL-1 have not been investigated." (PMID 32203216, 2020). "Since we evaluated protein levels in neuroblastoma cell lines with high BCL2 expression levels and not in MCL1-dependent cell lines, it cannot be excluded that MCL1 is downregulated by idasanutlin treatment in the latter." (PMID 28915653, 2017). "In contrast to the efficacy of monotherapy, we found that the venetoclax/idasanutlin combination is synergistic independent of MCL1 or BCL2 expression levels, suggesting a wide applicability in neuroblastoma." (PMID 28915653, 2017). "To test the relative importance of Bcl2, Bcl-xL, and Mcl1, we used a small molecule chemical screen coupled with readouts for apoptotic cell death in two cell lines, the dopaminergic MN9D and the more commonly used non-dopaminergic neuroblastoma N2A cell line." (PMID 30479840, 2018). "We next treated MYCN-amplified neuroblastoma cells with a short time course of MLN8237, and found p4E-BP1 and MCL-1 were reduced prior to marked mitotic arrest, suggesting a contribution of MCL-1 downregulation independent of mitotic arrest." (PMID 26859456, 2016). "After 24 h treatment of neuroblastoma cell lines CHP126, KCNR and SJNB12 with nanomolar concentrations ABT199, shifting of BIM from BCL-2 to the anti-apoptotic protein MCL-1 was observed while no sequestration of released BIM by the anti-apoptotic protein BCL-XL was observed." (PMID 27056887, 2016). "Moreover, Mcl-1 depletion did (in contrast to survivin depletion) not affect UKF-NB-3 cell viability, suggesting that YM155-mediated survivin depletion is critical for the compound's effects on neuroblastoma cell viability." (PMID 27735941, 2016).
cervical carcinoma (48 papers, 1998 to 2025). A carcinoma arising from either the exocervical squamous epithelium or the endocervical glandular epithelium. "Overexpression of Mcl-1 has been associated with aggressive tumor features, resistance to treatment and poor prognosis in breast, gastric, ovarian & cervical cancers." (PMID 25409302, 2014). "This discovery provides insight into how MCL1 expression is regulated, and suggests therapeutic targets for rescuing the function of the MCL1 protein most commonly associated with human cervical cancer." (PMID 25386925, 2014). "In this study, we investigated the role played by miR-107, a miRNA associated with cervical cancer and its interaction with the suppressor MCL1." (PMID 25386925, 2014). "Our findings are also supported by the previous reports in gastric and cervical cancers demonstrating the association between high Mcl-1 protein expression with tumor size, histological grade, lymph node involvement, metastasis & poor clinical outcome." (PMID 25409302, 2014). "Except for Mcl-1 expression in cervical carcinomas, the expressions of these genes are associated with elevated p-Stat3 (Tyr705) with statistic significance (P<0.05)." (PMID 17311011, 2007). "Furthermore, increased levels of MCL1 are closely associated with the pathogenesis of cervical cancer, being associated with histological grade, tumor size, and lymph node involvement, and positively correlated with poor prognosis." (PMID 38972247, 2024). "Also, TMS-TMF-4f suppressed both constitutive and IL-6-inducible levels of phosphorylated STAT3 (p-STAT3) and associated proteins such as Mcl-1, cyclin D1, survivin, and c-Myc in both cervical cancer cells." (PMID 31816985, 2019). "Whether MCL1 up-regulation in human malignancies is causally linked to cervical cancer or a correlative finding that are not fully understood and still has not to be examined." (PMID 25386925, 2014). "Research found that combining arsenic trioxide with ABT-737 can enhance mitochondrial apoptosis and downregulation of Mcl-1 in cervical cancer cells, leading to a synergistic lethal impact." (PMID 41234537, 2025). "USP13, which is sits on chromosome 3q26 that is highly amplified in cervical cancer, plays a key role in regulating Mcl-1 expression in HPV+ cervical cancer cells." (PMID 40011575, 2025). "Here, we report that engineered exosomes-mediated transfer of hsa-miR-320a overcomes chemoresistance in cervical cancer cells via targeting Myeloid Cell Leukemia Sequence 1 (MCL1)." (PMID 35444548, 2022). "Depletion of circ_CEP128 increased paclitaxel sensitivity via targeting miR-432-5p/MCL1 in cervical cancer." (PMID 36438563, 2022). "In particular, IL-6 promotes the survival of cervical cancer cells by upregulating the anti-apoptotic protein Mcl-1 via activation of the PI3K/Akt pathway." (PMID 36310590, 2022). "Lower expression of miR-320a is found in cervical cancer which generally inhibits cancer progression by regulating Mcl-1." (PMID 36276982, 2022). "As USP13 depletion resulted in the inhibition of cell proliferation in cervical cancer cells, we investigated if this was due to the reduction in Mcl-1 levels." (PMID 33627786, 2021). "We further demonstrated that USP13 was required for the proliferation of HPV positive cervical cancer cells, at least in part via the deubiquitination and stabilisation of the pro-survival protein, Mcl-1." (PMID 33627786, 2021). "Previously, the DUBs OTUD1 and JOSD1 had been shown to regulate Mcl-1 expression in cervical cancer cells." (PMID 33627786, 2021). "Together, our data demonstrates that USP13 is a potential oncogene in cervical cancer that functions to stabilise the pro-survival protein Mcl-1, offering a potential therapeutic target for these cancers." (PMID 33627786, 2021). "In conclusion, we have identified that the DUB USP13 is a potential oncogene in cervical cancer that promotes proliferation by deubiquitinating and stabilising the pro-survival protein Mcl-1." (PMID 33627786, 2021).